EMID1 (EMI domain containing 1)
Synonyms: Emu1; hEmu1; EMI5
Tractability: Antibody: UniProt places it where antibodies can reach, with medium confidence; UniProt predicts a signal peptide or a membrane-spanning region; its Gene Ontology location is reachable by antibodies, with medium confidence. PROTAC: ubiquitination databases record sites on it.
Gene: Protein-coding gene on chromosome 22 (29,205,809 to 29,259,598, forward strand). Ensembl gene ENSG00000186998.
Subcellular location: Secreted, extracellular space, extracellular matrix
Pathways (Reactome):
Metabolism of proteins: O-linked glycosylation
Gene Ontology:
Cellular component: endoplasmic reticulum lumen; non-collagenous component of interstitial matrix; endoplasmic reticulum; extracellular matrix; Golgi apparatus
Genetic constraint (gnomAD): Loss-of-function variants: 40 observed, 52.38 expected, observed/expected ratio (o/e) 0.76, 90% interval 0.59 to 0.99. The upper end of that interval is the gene's LOEUF score, 0.99, which puts it in group 4 of 6, group 1 being the genes least tolerant of losing a copy. Missense variants: 582 observed, 557.03 expected, observed/expected ratio (o/e) 1.04, 90% interval 0.98 to 1.12. Synonymous variants: 242 observed, 205.68 expected, observed/expected ratio (o/e) 1.18, 90% interval 1.06 to 1.31.
Homologues: Orthologues: macaque EMID1 (95% identical), chimpanzee EMID1 (95% identical), guinea pig EMID1 (87% identical), pig EMID1 (82% identical), mouse Emid1 (81% identical), rat Emid1 (70% identical). Paralogues in human: COL11A1 (36% identical), COL5A1 (36% identical), COL11A2 (35% identical), COL5A3 (33% identical), COL1A1 (32% identical), COL4A5 (31% identical), COL2A1 (31% identical), COL4A1 (30% identical), COL4A2 (30% identical), COL4A3 (30% identical), COL5A2 (30% identical), COL4A4 (29% identical), and 25 more.
Diseases named in the same sentence as EMID1 in open-access papers:
EMID1 is named in the same sentence as 10 diseases in open-access papers, as found by Europe PMC text mining. Sharing a sentence is not in itself a finding about the gene and the disease. The quoted sentences say what the papers report.
breast cancer (3 papers, 2021 to 2024). A primary or metastatic malignant neoplasm involving the breast. "In conclusion, EMID1 is differentially expressed in highly metastatic cells in a mouse mammary tumor model." (PMID 34385585, 2021). "Comparative analysis with the well-established MCF-10A reference cell line revealed a significant upregulation of APOA5, CHAC1, EMID1, GOSR2, TCP1, and TMEM167A in breast cancer cell lines." (PMID 38300336, 2024). "Conversely, EMI domain containing 1 (EMID1) and sarcoglycan epsilon (SGCE) displayed hazard ratios less than 1, suggesting a favorable prognosis for breast cancer patients with higher expression levels." (PMID 38300336, 2024). "EMID1 is more than lung cancer and lung injury; however, no study has found a relationship between CXCL9 and breast cancer." (PMID 39493752, 2024).
lung adenocarcinoma (3 papers, 2022 to 2025). A carcinoma that arises from the lung and is characterized by the presence of malignant glandular epithelial cells. "EMID1 is associated with immune infiltration levels in lung adenocarcinoma, and overexpression of this gene leads to a favorable prognosis for cancer patients, indicating that EMID1 is an immune-related prognostic marker for lung adenocarcinoma." (PMID 40746884, 2025). "EMID1 represents a potential candidate gene that promotes metastasis and exhibits upregulation in lung adenocarcinoma, correlating with improved prognosis and immune infiltration." (PMID 38300336, 2024).
lung carcinoma (2 papers, 2022 to 2024). "Differential expression analysis formally confirmed that decreased EMID1 expression was significantly associated with advanced stage and metastasis of lung cancer." (PMID 36245990, 2022). "Therefore, compared with the high-expression group, patients with low EMID1 expression had a higher risk of developing lung cancer." (PMID 36245990, 2022). "The results revealed that low expression of EMID1 in LUAD was related to poor survival time and prognosis, as well as the progress of clinical pathology, such as late stage and metastasis of lung cancer." (PMID 36245990, 2022).
cancer (3 papers, 2021 to 2025). A tumor composed of atypical neoplastic, often pleomorphic cells that invade other tissues. "To further analyze the effect of EMID1 on pan-cancer, we used a forest plot to display the effects of high expression of EMID1 on the risk of various tumors." (PMID 36245990, 2022). "We present here the unique functions of EMID1 protein and its association with cancer metastasis." (PMID 34385585, 2021). "In this study, we revealed exclusive expression of EMID1 protein in chief cells of gastric fundic glands and β cells of pancreatic islets in adult normal human tissues and some cases of human cancers." (PMID 34385585, 2021). "We analyzed the tissue distribution of EMID1 protein expression in normal and cancer tissues of human body." (PMID 34385585, 2021). "Immunohistochemical analysis of human cancers revealed that various types of cancers expressed EMID1 protein in the cytoplasm." (PMID 34385585, 2021). "In this study, we identified some unique features of EMID1, which has been identified as a candidate molecule for promoting cancer metastasis in the murine model." (PMID 34385585, 2021). "This is the first paper to clarify the molecular functions of EMID1 and the protein expression in human normal and cancer tissues." (PMID 34385585, 2021). "The present study is the first to show that the expression of EMID1 is related to cancer and may be a prognostic biomarker of LUAD." (PMID 36245990, 2022). "In addition, the EMID1 protein was expressed in limited types of cells in normal adult human tissues and some human cancer cases." (PMID 34385585, 2021). "EMID1 protein is exclusively expressed in chief cells of the gastric fundic glands and β cells of pancreatic islets in adult human normal tissues and some human cancer cases." (PMID 34385585, 2021). "In addition, we aimed to clarify the distribution of EMID1 expression in adult human normal and cancer tissues." (PMID 34385585, 2021). "In addition, increased expression of EMID1 protein detected in some cases of human cancers implies that EMID1 might be a new therapeutic target for cancer treatment." (PMID 34385585, 2021). "In addition, there are some reports of comprehensive analysis of gene mutations and expression profiles in human cancers demonstrated that EMID1 is a potential candidate molecule associated with development or metastasis of cancers, but its molecular mechanism has not been clarified." (PMID 34385585, 2021). "We have not yet demonstrated that EMID1 can promote cancer metastasis in this study using an overexpression method." (PMID 34385585, 2021). "Interestingly, EMID1 protein in these normal and cancer tissues is localized not in the extracellular matrix but in the cytoplasm, which is unlike expression in mouse tumor cells." (PMID 34385585, 2021). "However, no study to date has investigated the role of EMID1 in the development of cancer." (PMID 36245990, 2022).
tumor (2 papers, 2021 to 2022). "A significant aspect of our study entailed EMID1 expression with reference to immune infiltration levels in LAUD and concluded a positive correlation with B cells, thereby indicating that EMID1 regulated tumor immunology." (PMID 36245990, 2022). "First, according to the expression of EMID1, 535 tumor samples were divided into two types: 267 cases of low expression and 268 cases of high expression." (PMID 36245990, 2022). "The Cox regression analysis suggested that residual tumor, high and low expression of EMID1, tumor stage, and primary therapy outcome affect the OS of LUAD." (PMID 36245990, 2022). "Immunofluorescence showed that EMID1 deposited on the dish surface forms a unique brush-like structure in vitro, and the protein was linearly localized around tumor nests, corresponding to the basement membrane, in vivo." (PMID 34385585, 2021). "We analyzed the localization of EMID1 protein within the extracellular matrix of mouse tumor cells and its function in cell-matrix interaction." (PMID 34385585, 2021). "The molecular functions of EMID1 regarding the intrinsic properties of tumor cells are promotion of cell proliferation and suppression of invasion." (PMID 34385585, 2021). "Next, we examined the localization of EMID1 in the tumor tissue of 66-4-EMID1 cells and 66HM cells that were orthotopically inoculated into the mammary fat pad of syngeneic mice." (PMID 34385585, 2021). "Our experiments indicated that secreted EMID1 protein was deposited on the matrix beneath tumor cells and disrupted cell-matrix adhesion, which led the cells to detach from the matrix to form multicellular spheroids." (PMID 34385585, 2021). "These three experiments indicate that EMID1 can promote cell proliferation through cell cycle progression in mouse tumor cell lines." (PMID 34385585, 2021). "The expression of EMID1 in tumor tissues was significantly lower than that in normal tissues." (PMID 36245990, 2022). "Overexpression and knockdown studies using mouse tumor cell lines identified two novel functions of EMID1: intracellular signaling involving enhancement of cell growth via cell cycle promotion and suppression of cell motility, and inhibition of cell–matrix adhesion by extracellularly secreted EMID1." (PMID 34385585, 2021). "Overexpression of EMID1 induced distinct morphological changes in tumor cells in vitro." (PMID 34385585, 2021). "EMID1 can promote cell proliferation and suppress migration and invasion of tumor cells in vitro." (PMID 34385585, 2021). "To explore the mRNA expression of EMID1 in normal human tissues, we combined GTEX and TCGA-LUAD datasets to study the expression of EMID1 in tumor tissues." (PMID 36245990, 2022). "In patients with LUAD, the decreased expression of EMID1 was significantly correlated with clinical stage (stage III vs. stage I, P=0.012; stage IV vs. stage I, P=0.009), tumor status (T3 vs. T1, P=0.041), lymph node (N2 vs. N0, P=0.007), and distant metastasis (M1 vs. M0, P=0.030)." (PMID 36245990, 2022). "At 8 weeks after orthotopic inoculation, overexpression of EMID1 did not increase either tumor weight or spontaneous metastasis to the lung." (PMID 34385585, 2021). "However, the mechanism of EMID1 regulating tumor-infiltrating B cells is not clear and additional research is needed." (PMID 36245990, 2022). "Meanwhile, the correlation between tumor-infiltrating immune cells and genes was assessed using CIBERSORT, and it was found that the level of B cell infiltration was positively correlated with the expression of EMID1, all of which were validated in the GEO and GEPIA databases." (PMID 36245990, 2022).
EMID1 also shares sentences with these, for which no sentence is quoted: Alzheimer’s dementia (1 paper); basal cell carcinoma (1); Down syndrome (1); glioma (1); hearing loss (1).